PCDH7 (protocadherin 7)
Synonyms: BH-Pcdh; BHPCDH; PPP1R120
Tractability: Antibody: its Gene Ontology location is reachable by antibodies, with high confidence; UniProt places it where antibodies can reach, with medium confidence; UniProt predicts a signal peptide or a membrane-spanning region; the Human Protein Atlas places it where antibodies can reach. PROTAC: ubiquitination databases record sites on it; its protein half-life has been measured.
Gene: Protein-coding gene on chromosome 4 (30,720,369 to 31,146,805, forward strand). Ensembl gene ENSG00000169851.
Subcellular location: Cell membrane
Subcellular location (Human Protein Atlas): Cell Junctions; Plasma membrane
Pathways (Reactome):
Signal Transduction: RHOA GTPase cycle; RHOB GTPase cycle
Hemostasis: Platelet degranulation
Gene Ontology:
Molecular function: cell adhesion molecule binding; calcium ion binding
Biological process: cell adhesion; homophilic cell-cell adhesion
Cellular component: cell junction; plasma membrane; glutamatergic synapse; platelet alpha granule membrane; membrane
Genetic constraint (gnomAD): Loss-of-function variants: 16 observed, 53.36 expected, observed/expected ratio (o/e) 0.3, 90% interval 0.2 to 0.46. The upper end of that interval is the gene's LOEUF score, 0.46, which puts it in group 2 of 6, group 1 being the genes least tolerant of losing a copy. Missense variants: 1,220 observed, 1,417.4 expected, observed/expected ratio (o/e) 0.86, 90% interval 0.82 to 0.9. Synonymous variants: 641 observed, 591.23 expected, observed/expected ratio (o/e) 1.08, 90% interval 1.01 to 1.16.
Homologues: Orthologues: chimpanzee PCDH7 (99% identical), macaque PCDH7 (99% identical), mouse Pcdh7 (98% identical), rat Pcdh7 (98% identical), guinea pig PCDH7 (98% identical), pig PCDH7 (98% identical), tropical clawed frog pcdh7 (86% identical), zebrafish pcdh7b (81% identical), rabbit PCDH7 (75% identical). Paralogues in human: PCDH1 (50% identical), PCDH9 (38% identical), PCDH11X (35% identical), PCDH11Y (34% identical), CDH23 (23% identical), PCDH20 (22% identical), DCHS1 (21% identical), DCHS2 (20% identical), CDHR2 (18% identical), CDH2 (17% identical), CDH4 (17% identical), CDH1 (15% identical), and 21 more.
Diseases named in the same sentence as PCDH7 in open-access papers:
PCDH7 is named in the same sentence as 56 diseases in open-access papers, as found by Europe PMC text mining. Sharing a sentence is not in itself a finding about the gene and the disease. The quoted sentences say what the papers report.
lung carcinoma (27 papers, 2016 to 2026). "We found that PCDH7 significantly enhances lung cancer development and is associated with cisplatin resistance, which provides the direction for the potential drug development targeting PCDH7." (PMID 37538171, 2023). "Genes KRT81, SPP1, PCDH7, SLC2A1, and TET1 were significantly upregulated in tumor tissues and associated with poor prognosis and survival, providing insights for exploring lung cancer biomarkers in future studies." (PMID 41415280, 2025). "Lung cancer cells produce protocadherin 7 (PCDH7), which facilitates the creation of connexin 43 (Cx43) gap junctions with astrocytes." (PMID 40076927, 2025). "KRT81, SPP1, PCDH7, SLC2A1, and TET1 are associated with poor prognosis and survival outcomes, providing novel insights for exploring lung cancer biomarkers." (PMID 41415280, 2025). "Breast and lung cancer cells express protocadherin 7 (PCDH7), facilitating the formation of gap junctions between cancer cells and astroglia using Cx43." (PMID 38069203, 2023). "In lung cancer, the enforced PCDH7 expression significantly accelerates lung tumorigenesis in mice harboring the KrasG12D mutation and potentiates MAPK pathway activation." (PMID 37063257, 2023). "The results of qRT-PCR indicated that PCDH7 is overexpressed in lung cancer cells compared to normal lung cells." (PMID 37538171, 2023). "In contrast to the promotive effects of PCDH7 in breast and lung cancer, downregulated PCDH7 correlates with advanced grade, larger tumor size, and poorer overall survival in bladder cancer and gastric cancer patients." (PMID 37063257, 2023). "Although PCDH7 has recently been shown to have the effect of accelerating the distant metastasis of lung cancer and breast cancer, some studies have also shown that PCDH7 has low expression in colorectal cancer, gastric cancer, and invasive bladder cancer." (PMID 36311939, 2022). "PCDH7 is a member of the cadherin superfamily and has been found to promote the metastasis of lung cancer cells." (PMID 34881236, 2021). "Lung cancer cells employ protocadherin 7 (PCDH7) to engage astrocytes and promote the establishment of carcinoma-astrocyte gap." (PMID 34336687, 2021). "In fact, the interaction of Pcdh7 with SET, a known oncoprotein that participates in cancer progression, has been shown to play an important role in Pcdh7-induced lung cancer transformation and tumorigenesis." (PMID 34884920, 2021). "Breast and lung cancer cells express protocadherin 7 (PCDH7), which assembles cancer cell-astrocyte gap junctions that are made up of connexin 43 (Cx43)." (PMID 33466236, 2021). "They identified that overactivation of PCDH7 has led to tumorigenesis in KRASG12D-driven lung cancer, and it had also triggered MAPK signalling." (PMID 34781949, 2021). "A second neuronal gene upregulated in breast and lung cancer cells with brain tropism is protocadherin-7 (PCDH7)." (PMID 27618016, 2016). "Furthermore, lung cancer cells communicate with reactive astrocytes to upregulate protocadherin 7 (PCDH7), which promotes the formation of connexin 43 (Cx43) gap junctions, allowing the transfer of cyclic GMP–AMP (cGAMP) into astrocytes." (PMID 41429896, 2025). "Additionally, the promoter of PCDH7, a protocadherin gene with an oncogenic function in lung cancer, was hypermethylated in nine patients." (PMID 37742993, 2023). "Here, we found that PCDH7 may be involved in cisplatin resistance in lung cancer through public database analysis (GSE21656 and GSE108214)." (PMID 37538171, 2023). "PCDH7 can act as an independent lung cancer prognosis marker and a potential therapeutic target." (PMID 35372503, 2022). "However, increased PCDH7 expression has been reported in nonsmall cell lung cancer and castration-resistant prostate cancer/neuroendocrine prostate cancer." (PMID 33963380, 2021).
lung carcinoma (continued). "Additionally, recent studies proved that protocadherin 7 (PCDH7) expressed by breast and lung cancer cells could promote the carcinoma–astrocyte gap junction mediated by connexin 43 (Cx43)." (PMID 36761422, 2022). "PCDH7 could promote the malignant transformation of bronchial epithelial cells carrying KRAS gene mutation, while knockdown of PCDH7 inhibited the growth and metastasis of lung cancer cells with a mutated KRAS gene, suggesting that PCDH7 and KRAS had a synergistic cancer-promoting effect." (PMID 36117156, 2022). "Hence, inhibiting PCDH7 has been suggested as a critical strategy in lung cancer therapy." (PMID 34781949, 2021). "During our analysis, increased expressions of PCDH7, DEPDC1B, SATB2, and S100P were detected in lung cancer tissues and adjacent normal tissue of TCGA-LUAD patients, but expression of FGD3 was observed to be lower." (PMID 36530971, 2022). "PCDH7 could bind to the regulatory protein SET of PP2A, inhibiting PP2A activity, leading to dysregulation of negative feedback in the MAPK pathway, which in turn affected lung cancer progression." (PMID 36117156, 2022).
gastric cancer (11 papers, 2020 to 2024). A primary or metastatic malignant neoplasm involving the stomach. "Moreover, while PCDH7 expression was found to be upregulated in lung and breast cancer and associated with poor clinical outcome, decreased PCDH7 expression was documented in bladder and gastric cancers that unfavorably impact patient survival." (PMID 32457908, 2020). "Conversely, upregulation of PRMT6 in gastric cancer cells has been found to enhance invasion by inhibiting the transcription of the oncogene protocadherin 7 (PCDH7) through increased levels of H3R2me2as." (PMID 39043634, 2024). "PCDH7 plays a role in many cancers, including lung adenocarcinoma and gastric cancer, colon, ovarian, and breast cancers." (PMID 37476411, 2023). "In gastric cancer, knockdown of PCDH7 enhances cell migration and invasion, and PCDH7 can act as a tumor suppressor to inhibit cell migration and invasion by inhibiting cadherin." (PMID 37894938, 2023). "Although numerous previous reports have illustrated the promotion of lung and breast cancer cell migration and invasion by PCDH7, the increase in this protein inhibits cell migration and invasion in gastric cancer cells." (PMID 37063257, 2023). "In these previous studies, the downregulation of E-cadherin expression followed by PCDH7 depletion was believed to contribute to an increased potential in the migration and invasion of gastric cancer cells." (PMID 37063257, 2023). "For example, decreased PCDH7 expression has been reported in colorectal, bladder, and gastric cancer." (PMID 33963380, 2021). "Among the enriched pathways related to poor prognosis, five theranostic markers of interest were identified as deregulated and enriched in gastric cancer, including vWF, FN1, THBS1, PCDH7, and F5." (PMID 39456895, 2024). "However, in gastric cancer PRMT6-KO-GC cells, knockdown of tumor suppressor gene PCDH7 promoted cell migration and invasion." (PMID 38167455, 2024). "For example, PCDH7 was found to promote cell proliferation in MDA-MB-231 breast cancer cells, but failed to do so in BGC-823 and MKN-45 gastric cancer cells, and MCF7 and MDA-MB-436 breast cancer cells in this study." (PMID 32457908, 2020).
epilepsy (10 papers, 2014 to 2025). A brain disorder characterized by episodes of abnormally increased neuronal discharge resulting in transient episodes of sensory or motor neurological dysfunction, or psychic dysfunction. "Most of the genes known to cause or contribute to epilepsy can be traced to the synapse, including PCDH7, which is located in the excitatory synaptic cleft, and interacts with the NMDA receptor subunit GluN1." (PMID 40870033, 2025). "PCDH7 has been strongly associated with epilepsy in multiple genome-wide association studies (GWAS), as well as with schizophrenia, PTSD, and childhood aggression." (PMID 40870033, 2025). "We observed robust Pcdh7 expression, particularly in brain regions implicated in epilepsy, such as the hippocampus and cortex, consistent with previous studies in rodents." (PMID 40870033, 2025). "Genome-wide association studies have linked PCDH7 to epilepsy, shorter sleep, and antipsychotic treatment responses in schizophrenic patients." (PMID 38474013, 2024). "An international GWAS meta-analysis including 8,696 epilepsy patients and 26,157 controls highlights PCDH7 as susceptibility gene for epilepsy in general and GGE syndromes in particular." (PMID 25950944, 2015). "Specifically, PCDH7 has been associated with multiple neurological disorders, including epilepsy." (PMID 40870033, 2025). "PCDH7 is highly expressed in the brain and has been linked to CNS disorders, including epilepsy." (PMID 32616769, 2020). "Therefore, our findings may provide an explanation for the association of PCDH7 with epilepsy in humans." (PMID 40870033, 2025). "Although much of the research on PCDH7 pathogenic variants has primarily focused on its role in cancer, genome-wide association studies (GWAS) have linked PCDH7 to various neurological disorders, including epilepsy, schizophrenia, PTSD, and childhood aggression." (PMID 40870033, 2025). "Microdeletions found only in GGE patients harboured a high proportion of genes previously associated with epilepsy and neuropsychiatric disorders (NRXN1, RBFOX1, PCDH7, KCNA2, EPM2A, RORB, PLCB1)." (PMID 25950944, 2015). "A second signal for the all-epilepsy phenotype was located at 4p15.1 and included the 3′ end of the protocadherin gene, PCDH7." (PMID 25087078, 2014). "Although achieving genome-wide significance only for the all-epilepsy phenotype, the PCDH7 signal seemed stronger in genetic generalised epilepsy than in focal epilepsy." (PMID 25087078, 2014). "PCDH7 has been strongly linked to epilepsy; however, we did not observe spontaneous seizures in any mice from all genotypes at any developmental time point." (PMID 40870033, 2025). "This initial characterization of the Pcdh7 mouse model reveals that, despite widespread expression in the CNS and its association with human epilepsy, Pcdh7 function is not essential for murine brain development." (PMID 40870033, 2025). "The Pcdh7+/− genotype is the one carried by patients identified with epilepsy through GWAS." (PMID 40870033, 2025). "PCDH7 and KRTAP8-1 were high-frequency variants in epilepsy patients with PCOS, which could be associated with the susceptibility to PCOS in epilepsy patients." (PMID 40217327, 2023). "These microdeletions affected 158 protein-coding RefSeq genes and exhibited an enrichment of genes previously associated with epilepsy (NRXN1, RBFOX1, PCDH7, KCNA2, EPM2A, RORB, PLCB1) and neuropsychiatric disorders (DPYD, CADM2, PARK2, GRM8, TSNARE1, TPH2, MACROD2)." (PMID 25950944, 2015). "Meta-analysis of the all-epilepsy cohort identified loci at 2q24.3 (p=8·71 × 10−10), implicating SCN1A, and at 4p15.1 (p=5·44 × 10−9), harbouring PCDH7, which encodes a protocadherin molecule not previously implicated in epilepsy." (PMID 25087078, 2014). "PCDH7 encodes a calcium-dependent adhesion protein, not previously associated with epilepsy." (PMID 25087078, 2014).
epilepsy (continued). "The analysis identified polymorphic sequence variants as risk factors for the combined cohorts (focal and GGE) in SCN1A—perhaps the most well—known epilepsy gene—and in protocadherin 7 (PCHD7), a gene not yet known to be associated with epilepsy." (PMID 26302787, 2015). "However, a seizure susceptibility assay revealed increased latencies in Pcdh7+/− mice, but not in Pcdh7+/+ and Pcdh7−/− mice, potentially explaining the association of PCDH7 with epilepsy." (PMID 40870033, 2025).
breast carcinoma (8 papers, 2017 to 2025). "PCDH7 was identified as one of the top-ranking genes associated with breast cancer metastasis to the brain." (PMID 37063257, 2023). "PCDH7 (protocadherin 7) was reported to be related to cell growth, development and progression in prostate cancer, cervical cancer and breast cancer." (PMID 40362181, 2025). "Reduction of PCDH7 in the metastatic breast cancer cell line MDA-MB-231 effectively inhibits cell proliferation, migration, and invasion in vitro." (PMID 37063257, 2023). "PCDH7 was shown to promote transformation and metastasis in several types of cancers including lung, prostate and breast cancer." (PMID 32457908, 2020). "A gene list initially reported as commonly deregulated in brain tropic cancer cells from lung and breast cancer, included the protocadherin 7 (PCDH7)." (PMID 29312881, 2017). "Interestingly, MBNL2 has been recently reported to control hypoxia response in breast cancer cells and PCDH7 was reported to induce bone metastasis of breast cancer cells." (PMID 35697736, 2022). "Importantly, in MCF-7 breast cancer cells as a model of Luminal A subtype breast cancers, GPR81-regulated genes were significantly associated with multiple GO terms relating to extracellular matrix (ECM) and cell adhesion, including PCDH7, EPHA7, and the Notch ligand DLL4." (PMID 37993804, 2023).
colorectal cancer (7 papers, 2016 to 2024). A primary or metastatic malignant neoplasm that affects the colon or rectum. "Subsequently, we attempted to identify the potential targets of PCDH7 in colorectal cancer cells to further elucidate the underlying mechanism of its role in the development of drug resistance in CRC." (PMID 37063257, 2023). "To further examine the potential effect of PCDH7 on drug resistance in colorectal cancer, we performed gain- and loss-of-function experiments by overexpressing or knocking down PCDH7 in colorectal cancer cells." (PMID 37063257, 2023). "Association between PCDH7 expression and clinical pathological features in colorectal cancer patients." (PMID 37063257, 2023). "Additionally, the combination of the Mcl-1 inhibitor S63845 with ABT-263 can eliminate chemoresistance caused by abundant PCDH7 in colorectal cancer cells." (PMID 37063257, 2023). "To further confirm that PCDH7 affected colorectal cancer chemoresistance mainly through Mcl-1 expression, we applied an Mcl-1 inhibitor, S63845, in HCT116 cells coupled with PCDH7 overexpression." (PMID 37063257, 2023). "Cell proliferation was detected in colorectal cancer cell lines by PCDH7 overexpression or silencing using the MTT assay." (PMID 37063257, 2023). "Because the Mcl-1 and Wnt/β-catenin signaling pathways were molecularly identified as regulatory targets of PCDH7, we discovered a combination of the Mcl-1 inhibitor S63845 and ABT-263 as a novel chemotherapy treatment option for PCDH7-high colorectal cancer." (PMID 37063257, 2023). "In the current study, we found that different colorectal cancer cells expressed PCDH7 over a wide range." (PMID 37063257, 2023). "To investigate the potential functions of PCDH7 in colorectal cancer, we initially used Western blotting to detect the abundance of PCDH7 in different colorectal tumor cell lines, including LS411N, DLD1, RKO, HCT116, SW620, HT29, and SW480." (PMID 37063257, 2023). "In the present study, we found that PCDH7 conferred higher cell proliferation potential and stronger chemoresistance in colorectal cancer cells both in vitro and in vivo by promoting MCL-1 expression." (PMID 37063257, 2023). "Together, these results revealed that abundant PCDH7 enhances the resistance of colorectal cancer cells to chemotherapeutic drug treatment to facilitate cell viability, suggesting that PCDH7 is a potential regulatory target for colorectal cancer chemotherapy." (PMID 37063257, 2023). "Given the widely known role of protocadherin in cell-in-cell structure to mediate cancer cell metastasis, we further determined whether PCDH7 could contribute to colorectal cancer metastasis by regulating cancer cell migration and invasion." (PMID 37063257, 2023). "In summary, our data implied that PCDH7 could potentially play a role in colorectal cancer progression by accelerating cancer cell proliferation." (PMID 37063257, 2023). "Mechanistically, the overexpression of AQP8 inhibits the expression of PCDH7 through the PI3K/AKT signaling pathway, thereby inhibiting the growth and metastasis of colorectal cancer cells." (PMID 32462020, 2020). "Taken together, although PCDH7 inhibited the migration and invasion of CRC cells, it could facilitate the development of drug resistance in colorectal cancer cells by positively modulating Mcl-1 expression." (PMID 37063257, 2023). "AQP8 overexpression in the colorectal cancer cell lines SW480 and HT-29 inhibited the growth and invasion of colorectal cancer cells by inactivating the PI3K/AKT signaling pathway and inhibiting PCDH7 expression." (PMID 37280594, 2023). "To characterize the potential effects of PCDH7 on colorectal cancer, we successfully induced the expression of PCDH7 in SW480, HT29, HCT116, LS411N, and SW620 cells using an overexpression plasmid, while decreasing PCDH7 expression in DLD1 and RKO cells by transfection with a siRNA against PCDH7." (PMID 37063257, 2023).
colorectal cancer (continued). "As anticipated, the protein expression of Mcl-1 was upregulated following PCDH7 overexpression in HCT116 cells and downregulated after PCDH7 knockdown in RKO cells, which may partially explain the anti-apoptotic effect exerted by PCDH7 on colorectal cancer cells." (PMID 37063257, 2023). "Indeed, AQP8 may inhibit colorectal cancer growth and metastasis by decreasing PI3K/AKT signaling and PCDH7 expression; thus, AQP8 status in colorectal carcinoma has a potential clinical significance." (PMID 32457800, 2020).